L3HYPDH (trans-L-3-hydroxyproline dehydratase)
Description:
Catalyzes the dehydration of trans-3-hydroxy-L-proline to Delta(1)-pyrroline-2-carboxylate (Pyr2C). May be required to degrade trans-3-hydroxy-L-proline from the diet and originating from the degradation of proteins such as collagen-IV that contain it.
Synonyms: C14orf149; FLJ25436
Tractability: PROTAC: ubiquitination databases record sites on it; its protein half-life has been measured.
Gene: Protein-coding gene on chromosome 14 (59,460,363 to 59,484,408, reverse strand). Ensembl gene ENSG00000126790.
Subcellular location (Human Protein Atlas): Vesicles
Gene Ontology:
Molecular function: hydro-lyase activity; proline racemase activity; trans-L-3-hydroxyproline dehydratase activity
Genetic constraint (gnomAD): Loss-of-function variants: 31 observed, 22.92 expected, observed/expected ratio (o/e) 1.35, 90% interval 1.01 to 1.79. The synonymous counts are far from expectation, so gnomAD's model fits this gene poorly and the ratio says little. Missense variants: 522 observed, 423.99 expected, observed/expected ratio (o/e) 1.23, 90% interval 1.14 to 1.32. Synonymous variants: 207 observed, 163.06 expected, observed/expected ratio (o/e) 1.27, 90% interval 1.13 to 1.42.
Homologues: Orthologues: chimpanzee L3HYPDH (99% identical), dog L3HYPDH (92% identical), rabbit L3HYPDH (92% identical), pig L3HYPDH (91% identical), mouse L3hypdh (89% identical), macaque L3HYPDH (88% identical), guinea pig L3HYPDH (87% identical), zebrafish l3hypdh (70% identical), tropical clawed frog l3hypdh (69% identical).